LINC00173 (long independently transcribed non-coding RNA 173)
Synonyms: NCRNA00173; FLJ42957
Gene: Long non-coding RNA gene on chromosome 12 (116,533,399 to 116,536,522, forward strand). Ensembl gene ENSG00000196668.
Diseases named in the same sentence as LINC00173 in open-access papers:
LINC00173 is named in the same sentence as 25 diseases in open-access papers, as found by Europe PMC text mining. Sharing a sentence is not in itself a finding about the gene and the disease. The quoted sentences say what the papers report.
lung carcinoma (4 papers, 2020 to 2023). "To discover novel functions of LINC00173, we first focused on the SNAIL family of zinc finger transcription factors, involved in cancer progression and recurrence in various human cancers, including lung cancer, as a candidate interacting partner of LINC00173." (PMID 38069335, 2023). "This study might provide an insight into the diverse roles of LINC00173 in different histologic types of lung cancer and provide a distinctive chemotherapeutic strategy for patients with LUAD differing from SCLC or LUSC." (PMID 36627670, 2023). "In this LINC00173-SNAIL-FHIT axis, FHIT acts as a tumor suppressor to inhibit carcinogenesis and tumor progression in lung cancer." (PMID 38069335, 2023). "Overexpression of PART1, SNHG11, LINC00173 and MIR17HG is widely involved in tumorigenesis and malignant progression of several types of cancer, such as glioma, breast cancer, lung cancer and colorectal cancer." (PMID 34243770, 2021).
lung squamous cell carcinoma (4 papers, 2021 to 2024). "For instance, LINC00173 is associated with the tumorigenesis of various cancers, including glioma, lung squamous cell carcinoma and colorectal cancer." (PMID 37081063, 2023). "LINC00173 promotes the proliferation and migration of vascular endothelial cells, which is related to the angiogenesis and tumorigenesis of lung squamous cell carcinoma." (PMID 38921668, 2024). "Previous study had found that LINC00173 promotes the proliferation and migration of vascular endothelial cells in lung squamous cell carcinoma by acting as ceRNA to bind with miR-511-5p and regulate VEGFA expression." (PMID 34603387, 2021). "LINC00173 had been reported as a cisplatin (cis-diamminedichloroplatinum, DDP) chemotherapy-resistant inducer in small-cell lung cancer (SCLC) and lung squamous cell carcinoma (LUSC)." (PMID 36627670, 2023).
glioma (3 papers, 2021 to 2023). A benign or malignant brain and spinal cord tumor that arises from glial cells (astrocytes, oligodendrocytes, ependymal cells). "Taken together, LINC00173 interacts with the same miRNA, miR-765, to exert its regulatory function in both glioma and CRC." (PMID 36497407, 2022). "In glioma, LINC00173 sponges miR-765 to upregulate the expression of NUTF2 expression, and NUTF2 overexpression further promotes the proliferation, migration, and invasion of glioma cells, suggesting that LINC00173 functions as a critical oncogenic lncRNA in glioma." (PMID 36497407, 2022).
breast carcinoma (2 papers, 2021 to 2023). "This indicates that there may be a regulatory mechanism involving a LINC00173-SNAIL-FHIT axis in breast cancer, but that it may not convey a large enough effect to affect the breast cancer prognosis." (PMID 38069335, 2023).
cervical cancer (2 papers, 2022 to 2023). A primary or metastatic malignant neoplasm involving the cervix. "Conversely, LINC00173 is reported to be downregulated in cervical cancer, and it inhibits cell proliferation and invasion by regulating the miR‐182‐5p/FBXW7 axis." (PMID 36606322, 2023). "Interestingly, in two independent studies on cervical cancer, LINC00173 plays a dual role as a promoter and inhibitor, which may be attributed to the different biological functions it targets." (PMID 36213821, 2022).
lung adenocarcinoma (2 papers, 2023). A carcinoma that arises from the lung and is characterized by the presence of malignant glandular epithelial cells. "Taking these findings together, we conclude that the LINC00173-SNAIL-FHIT axis identified in the A549 cell line is also present in patients with lung adenocarcinoma." (PMID 38069335, 2023). "Data from 501 patients with lung adenocarcinoma also support the existence of a LINC00173-SNAIL-FHIT axis, as FHIT expression correlated positively with LINC00173 (p = 1.75 × 10−6) and negatively with SNAIL (p = 7.00 × 10−5)." (PMID 38069335, 2023). "Among them, we focused on the non-small cell lung cancer, lung adenocarcinoma, in which LINC00173 acts as a suppressor of tumorigenesis and tumor progression." (PMID 38069335, 2023). "This indicates that the LINC00173-SNAIL-FHIT axis also exists in patients with lung adenocarcinoma, where LINC00173 acts as a tumor suppressor." (PMID 38069335, 2023). "In this study, we propose a model in which LINC00173 positively regulates FHIT expression by repressing SNAIL function in human lung adenocarcinoma." (PMID 38069335, 2023). "We next examined whether the LINC00173-SNAIL-FHIT axis identified in the lung adenocarcinoma cell line A549 is also observed in cancer patients." (PMID 38069335, 2023). "Although the detection of FHIT may be sufficient for prognosis, the expression status and genetic defects of LINC00173 in pre-cancerous or actual lung adenocarcinoma may also be a potential biomarker for carcinogenesis and progression of lung adenocarcinoma." (PMID 38069335, 2023). "Taken together, we propose that LINC00173 positively regulates FHIT gene expression by binding to SNAIL and inhibiting its function in human lung adenocarcinoma." (PMID 38069335, 2023). "Thus, this study sheds light on the LINC00173-SNAIL-FHIT axis, which may be a key mechanism for carcinogenesis and progression in human lung adenocarcinoma." (PMID 38069335, 2023).
nasopharyngeal carcinoma (2 papers, 2023). A carcinoma arising from the nasopharyngeal epithelium. "Our study shows that LINC00173 is upregulated in nasopharyngeal carcinoma (NPC) and is associated with poor prognosis of patients." (PMID 36606322, 2023). "The reversal of LINC00173-mediated cancer cell progression by SDF4 knockdown suggested the potential of the LINC00173-RAB1B-SDF4 pathway to be a drug target for nasopharyngeal cancer." (PMID 38259614, 2023).
non-small cell lung carcinoma (2 papers, 2022 to 2023). A group of at least three distinct histological types of lung cancer, including non-small cell squamous cell carcinoma, adenocarcinoma, and large cell carcinoma. "In contrast, LINC00173 is downregulated in cervical cancer (CC), acute myeloid leukemia (AML), and non-small cell lung cancer (NSCLC)." (PMID 36497407, 2022).
cervical squamous cell carcinoma (1 paper, 2023). A squamous cell carcinoma arising from the cervical epithelium. "Using the cervical squamous cell carcinoma dataset, we performed Kaplan–Meier analysis and found that the prognosis of the patient group with low LINC00173 expression was significantly poor (p = 0.018), which is consistent with a previous report showing that LINC00173 acts as a tumor suppressor." (PMID 38069335, 2023).
congenital neutropenia (1 paper, 2017). "Future studies will need to investigate whether modulating LINC00173 expression can instruct or block granulocytic differentiation in patients with perturbed granulopoiesis, such as severe congenital neutropenia (Kostmann’s disease)." (PMID 28794406, 2017).
endometriosis (1 paper, 2025). The growth of functional endometrial tissue in anatomic sites outside the uterine body. "A transcriptomic analysis revealed key miRNAs and lnCRNA implicated in endometriosis and RIF, including miR-9, miR-34, and miR-135a/b miR-30d-5p, PART1, MIR17HG, H19, LINC00173, NEAT1, and LINC01960-201." (PMID 39858500, 2025).
leukemia (1 paper, 2022). A malignant (clonal) hematologic disorder, involving hematopoietic stem cells and characterized by the presence of primitive or atypical myeloid or lymphoid cells in the bone marrow and the blood. "To note, by analyzing five leukemia cell lines (HL60, K652, REH, SUPB15, and MOLT), we found that K562 displays the highest expression level of LINC00173." (PMID 35719952, 2022).
small cell lung carcinoma (1 paper, 2020). Small cell lung cancer (SCLC) is a highly aggressive malignant neoplasm, accounting for 10-15% of lung cancer cases, characterized byrapid growth, and early metastasis. "This may be explained why LINC00173 was found to be highly expressed in chemoresistant small-cell lung cancer (SCLC) cell lines, and was significantly correlated with chemoresistance and progression in SCLC patients." (PMID 32473645, 2020).
squamous cell carcinoma (1 paper, 2025). A carcinoma arising from squamous epithelial cells. "Overexpression of LINC00173 has been shown to promote the proliferation and migration of vascular endothelial cells and tumorigenesis of squamous cell carcinoma cells both in vitro and in vivo." (PMID 41327671, 2025).
triple-negative breast carcinoma (1 paper, 2023). An invasive breast carcinoma which is negative for expression of estrogen receptor (ER), progesterone receptor (PR), and human epidermal growth factor receptor 2 (HER2). "For instance, LINC00173 facilitates the progression of triple negative breast cancer by inhibiting miR‐490‐3p expression." (PMID 36606322, 2023).
cancer (10 papers, 2017 to 2024). A tumor composed of atypical neoplastic, often pleomorphic cells that invade other tissues. "Along with our BCP-ALL findings, we detected an abnormal expression of LINC00173 in many human cancer types and an association with reduced OS." (PMID 35719952, 2022). "Inversely, LINC00173 expression was negatively associated with gene sets involved in stemness and cancer, as well as cell cycle progression." (PMID 28794406, 2017). "LINC00173 is associated with various types of human cancer in a cell context-dependent manner." (PMID 38069335, 2023). "Additionally, data from diverse solid tumors reveal that LINC00173 acts as a competitive endogenous RNA (ceRNA) and is associated with cancer-related processes and chemoresistance." (PMID 35719952, 2022). "Likewise, other studies have shown that LINC00173 is associated with cancer-related processes including proliferation, migration, invasion, metastasis, inhibition of apoptosis, and chemoresistance." (PMID 35719952, 2022). "Currently, LINC00173 has been reported to function as a cancer promoting or suppressing factor in different tumors." (PMID 36606322, 2023). "In summary, LINC00173 can serve as a potential drug target for chemotherapy in multiple human cancers." (PMID 36497407, 2022). "Meanwhile, dysregulated LINC00173 is involved in several physiological and pathological processes of human cancers with multiple functions and mechanisms." (PMID 36497407, 2022). "In this paper, we summarized the roles of LINC00173 in some different cancers and the molecular mechanism, including tumorigenesis, chemoresistance, and its regulatory targets." (PMID 36497407, 2022). "Biological functional studies in vitro have shown that overexpression of LINC00173 increases cancer cell apoptosis while inhibiting PCA cell invasion and proliferation." (PMID 36497407, 2022). "The knowledge that LINC00173 is abnormally expressed in most human cancer types exhibits this lincRNA as a relevant gene in the oncogenesis process; thus, we need to delve into the molecular mechanisms involving LINC00173 in human malignancies." (PMID 35719952, 2022). "In SCLC, LINC00173 promotes the proliferation, migration, invasion, chemoresistance, and tumorigenesis of cancer cells by targeting miR-218 to modulate Etk expression." (PMID 36497407, 2022). "Subsequently, the assessment of inhibitory concentration 50% (IC50) value and cancer cell viability shows that LINC00173 overexpression can promote the CDDP resistance of HQ-MT cells." (PMID 36497407, 2022). "In this study, we focused on the role of LINC00173 in tumorigenesis and cancer progression." (PMID 38069335, 2023). "To identify target genes of LINC00173 involved in human cancer, we performed RNA-seq analysis on RNA samples prepared from A549 cells transfected with two independent antisense oligonucleotides (ASOs) for LINC00173 (ASO-173 #1 and #2) and a negative control ASO (ASO-NC)." (PMID 38069335, 2023). "This review systematically summarizes the latest findings concerning the expression and the regulatory mechanisms of LINC00173, which covers the tumorigenesis and chemoresistance, and regulatory targets of LINC00173, thus providing a novel biomarker for cancer prognosis and a therapeutic target." (PMID 36497407, 2022). "Aberrant expression of LINC00173 affects the initiation and progression of human cancers." (PMID 36497407, 2022). "Through the summary of the abnormal expression of LINC00173 and its potential molecular regulation mechanism in cancers, this article indicates that LINC00173 may serve as a potential diagnostic biomarker and a target for drug therapy, thus providing novel clues for future related research." (PMID 36497407, 2022). "Since LINC00173 was either under- or overexpressed in all human cancer types deposited in TCGA, it is likely that this gene could act as an oncogene and a tumor suppressor gene by controlling relevant processes in cancer." (PMID 35719952, 2022).
cancer (continued). "We aimed to investigate whether LINC00173 is a biomarker in ALL and to explore its expression level in other human cancer types." (PMID 35719952, 2022). "Previous studies have correlated cancer-related functions with AL360004.1, LINC00173, LINC01089 and LINC00115; however, none of them have been linked to the pathogenesis of AIS." (PMID 35401659, 2022).
tumor (6 papers, 2022 to 2025). "TCGA data analysis revealed that underexpression of LINC00173 is also associated with poor clinical outcomes in six new reported tumor types." (PMID 35719952, 2022). "Investigating the clinicopathological parameters revealed a correlation between high LINC00173 expression, tumor metastases, and tumor histological type." (PMID 39912974, 2025). "We found that LINC00173 expression is deregulated in all tumors, being underexpressed in 13 different tumor types (Log2FC > 1, p < 0.01)." (PMID 35719952, 2022). "LINC00173 expression is correlated with tumor metastases and tumor histological type." (PMID 39912974, 2025). "Due to our findings in ALL and because some studies have reported an abnormal expression of LINC00173 in different malignancies, we screened the LINC00173 expression in 33 tumor types and their correspondent normal tissues, whose data are available in the TCGA repository." (PMID 35719952, 2022). "Additionally, LINC00173 depletion restrained WT tumor growth and metastasis in vivo." (PMID 36497407, 2022). "In addition, the overexpression of LINC00173 attenuated tumorigenicity in xenograft tumor models." (PMID 36497407, 2022). "To explore whether LINC00173 promotes the growth of NPC cells in vivo, we established subcutaneous tumor models using SUNE1 cells stably expressing sh0173 or shCtrl." (PMID 36606322, 2023). "The aim of the present study was to investigate whether LINC00173 is as potential biomarker in BCP-ALL and to explore its expression in other tumor types by using publicly available data in The Cancer Genome Atlas (TCGA) repository." (PMID 35719952, 2022). "On the other hand, LINC00173 has been proven to serve as a vital regulator of several non-tumor diseases, such as hypertrophic scar fibroblasts and polycystic ovarian syndrome (PCOS), regulating a series of basic life activities, including cell proliferation, differentiation, and apoptosis." (PMID 36497407, 2022). "Some of them have been reported previously, but underexpression and overexpression of LINC00173 were observed in six (DLBC, KICH, OV, THCA, UCEC, and UCS) and one (KIRC) non-reported tumor type, respectively." (PMID 35719952, 2022).
LINC00173 also shares sentences with these, for which no sentence is quoted: acute myeloid leukemia (1 paper); AIDS (1); colorectal cancer (1); Kostmann’s disease (1); leishmaniasis (1); leprosy (1); malaria (1); tuberculosis (1).